INS (insulin)
Diseases named in the same sentence as INS in open-access papers (continued):
Sharing a sentence is not in itself a finding about the gene and the disease.
diabetes (continued). "Age and type of medication – no medication, oral medication or oral medication and insulin – were the strongest indicators for diabetes-related primary healthcare profiles." (PMID 23289605, 2013). "No overt trends in prandial or basal insulin use by diabetes duration were observed, although there was a small increase in the use of basal-bolus therapy with increasing diabetes duration." (PMID 23800082, 2013). "“In this type of diabetes, there is some insulin in the body but not enough to maintain good health, indicating that it usually occurs in middle and older aged groups”." (PMID 24171871, 2013). "Given that neither deletion nor constitutive activation of TG2 transamidase activity altered basal responses, or responses to a glucose or insulin challenge, our data indicate that glucose homeostasis in mice is TG2 independent, and question a link between TG2 and diabetes." (PMID 23717413, 2013). "The two animals that developed diabetes had severe insulitis and lacked insulin staining in the islets (similar to phenotype 2 noted in the control animals, data not shown)." (PMID 23704916, 2013). "Nevertheless, we have found that the incretin effect slope is lower when fasting or IIGI-stimulated insulin secretion is higher regardless of diabetes status." (PMID 24019903, 2013). "We had no information on type 1 or type 2 diabetes, but a sensitivity analysis excluding people who were diagnosed with diabetes before <40 years of age and who reported to use insulin injection suggest no large bias of the results." (PMID 23738538, 2013). "The rigid quantification of diabetes in 1970s and 1980s was not as specific as it is today for many reasons including the nonavailability of routine serum insulin evaluations, glycosalated haemoglobin, and other biochemical tests." (PMID 24396605, 2013). "In our study, men with diabetes had a significant 3.8-fold increase in CAC prevalence compared with insulin sensitive men without diabetes." (PMID 23341938, 2013). "Mice that lack Irs1 display profound growth retardation but do not develop diabetes because insulin secretion compensates for the presence of mild insulin resistance." (PMID 23741292, 2013). "Further, the amount of HMW adiponectin (18–30+ protomers) but not total adiponectin correlates to improved insulin sensitivity in mice and humans with type 2 diabetes mellitus." (PMID 24065958, 2013). "Type 1 diabetes mellitus (T1DM), which accounts for 5–10% of those with diabetes, results from a cellular-mediated autoimmune destruction of the pancreatic beta-cells, which renders patients insulin-dependent for life." (PMID 24386202, 2013). "In regard to preadmission diabetes medication regimen, oral antidiabetic drugs were the most common treatment reported (37.7%), followed by insulin alone (17.3%), and approximately one-quarter had no information registered on chart." (PMID 24499564, 2013). "LSR was not correlated to the duration of diabetes (p = 0.80) or HbA1c level (p = 0.21) and was not influenced by dedicated treatments especially insulin therapy (p = 0.46), the presence of retinopathy (p = 0.43) or peripheral vascular disease (p = 0.34)." (PMID 23759020, 2013). "I tend to forget to take or skip my diabetes medication (e. g. insulin, tablets). ☐ Diabetes medication / insulin is not required as a part of my treatment." (PMID 23937988, 2013). "The intensity of the insulin immunolabeling (red), an indication the insulin content/β-cell, was not different during the early stages of diabetes (less than 10 days duration)." (PMID 23762878, 2013). "Diabetes mellitus type 1 (DM1) is an endocrine disorder which is characterized by lack of insulin and hyperglycemia." (PMID 25938109, 2013). "Diabetes status was determined from response to a question ‘Has a doctor EVER told you that you have diabetes’ (n = 23,981) and augmented by examination of free text fields about diagnosis (n = 119) or use of insulin (n = 58)." (PMID 24245780, 2013).
diabetes (continued). "I did not want to be in a very serious category” (3 years of insulin use/ 8 years of having diabetes)." (PMID 24164794, 2013). "In these subjects, βCF – assessed by the insulin response during an oral glucose tolerance test (OGTT) – also seems to be impaired, especially in subjects older than 23 years, with a case of diabetes mellitus (DM) diagnosed in a 38-year-old patient due to βCF exhaustion." (PMID 23795286, 2013). "Mortality among people with non-insulin-treated diabetes compared to the non-diabetic population has decreased especially with regard to CVDs, whereas no decrease among insulin-treated were seen." (PMID 23837500, 2013). "The excess mortality rate for those with insulin-treated diabetes compared with those without diabetes remained stable except for increasing excess mortality from neoplasms." (PMID 23837500, 2013). "Although the increased prevalence of obesity and resulting insulin resistance is contributing to the increased prevalence of type 2 diabetes, many obese individuals are insulin resistant but do not develop diabetes." (PMID 23442068, 2013). "Type 2 diabetes mellitus (T2DM) is a metabolic disorder in which pancreatic insulin secretion does not meet the demands of insulin sensitivity." (PMID 23815372, 2013). "A key point is that most people with insulin resistance will never develop T2D: diabetes only results if their β cells fail to provide sufficient insulin." (PMID 23363033, 2013). "No system had inbuilt data quality checks (prescribing insulin without a diagnosis of diabetes for example)." (PMID 23939340, 2013). "Diabetes is a chronic disease that occurs when the pancreas does not produce enough insulin or when the body cannot effectively use the insulin it produces." (PMID 24324490, 2013). "Overt diabetes occurs when pancreatic β cells are no longer capable of intensive insulin production." (PMID 23476808, 2013). "About 20% of obese individuals appear to have normal insulin regulation and normal metabolic indices (no indication of diabetes) and normal longevity, while up to 40% of normal weight people in some populations manifest aspects of the “metabolic syndrome”." (PMID 23460912, 2013). "I had some doubts and was not very confident to start insulin therapy” (4 years of insulin use/ 10 years of having diabetes)." (PMID 24164794, 2013). "Diabetes is a chronic disease that occurs either when the pancreas does not produce enough insulin (a hormone that regulates blood sugar), known as type 1 diabetes, or when the body cannot effectively use the insulin it produces—type 2 diabetes." (PMID 23610560, 2013). "Decreasing mortality trends were found in people with and without diabetes in 1998–2007 except in mortality from neoplasms among insulin-treated persons." (PMID 23837500, 2013). "Insulin resistance, the condition in which normal insulin response is not produced by normal amounts of insulin, is a fundamental component of the pathogenesis of type 2 diabetes mellitus (T2D)." (PMID 24349514, 2013). "I take my diabetes medication (e. g. insulin, tablets) as prescribed. ☐ Diabetes medication / insulin is not required as a part of my treatment." (PMID 23937988, 2013). "Appropriate insulin therapy was given to no more than one third of inpatients with diabetes in our study." (PMID 24499564, 2013). "No type 1 patients received non-insulin diabetes medications at any time before or after CSII initiation." (PMID 27536441, 2013). "SPARC circulating levels are associated with HOMA-IR and HbA1c in obese individuals without diabetes and secretion from adipose tissue is induced by insulin." (PMID 23840838, 2013). "Patients who required insulin or oral medications before metabolic surgery were more likely to have improvement in their diabetes rather than remission of their diabetes." (PMID 23515973, 2013). "Contrary to non-insulin-treated people with diabetes, the excess mortality associated with CVD did not decrease among insulin-treated people." (PMID 23837500, 2013).
diabetes (continued). "The inverse association between serum leptin and increased risk of diabetes was independent of obesity in the Atherosclerosis Risk in Communities (ARIC), whereas it was mediated by adiposity and insulin insensitivity in a study among Japanese men and women." (PMID 24455217, 2013). "The endpoint for the study was diabetes reversal as defined by persistent reading of glucose levels under 250 mg/dL without insulin injections or after pump removal." (PMID 24023664, 2013). "Another study with insulin treatment in a murine model of obesity and diabetes mellitus type 2, the db/db mice, suggested no impact on adiponectin levels." (PMID 23497197, 2013). "This is confirmed by the lack of any effect of glucose-insulin infusions in the acute phase of myocardial infarction in patients without diabetes." (PMID 24348585, 2013). "The excess mortality rate for persons with non-insulin-treated diabetes compared to those without diabetes appears to be clearly diminishing." (PMID 23837500, 2013). "With the discovery of insulin in 1921 by Frederick Banting at the University of Toronto, diabetes, particularly type 1, was no longer a death sentence." (PMID 24278682, 2012). "This suggests that the pancreas has been able to modulate insulin secretion to maintain glucose homeostasis and these animals have not yet developed overt type 2 diabetes mellitus." (PMID 22442686, 2012). "Acute insulin responsiveness is subnormal in patients with HCV infection, demonstrating that it is unlikely that insulin resistance alone causes diabetes without underlying impairment of beta cells." (PMID 22675572, 2012). "Any patient, with or without diabetes, who requires insulin therapy in the perioperative period is evaluated by the Inpatient Diabetes Service to determine the best plan for glucose management at home." (PMID 23209941, 2012). "Our results were not simply due to differences in diabetes subtype or prandial exogenous insulin type." (PMID 22681724, 2012). "Blood pressure, insulin and glucose measures, which are important components of metabolic syndrome and risk factors for adult-onset CVD and diabetes, were not collected in this age group and thus were not available for analysis." (PMID 22685478, 2012). "Zucker Diabetic Fatty rats treated with or without insulin (ZDF ± Ins, n = 13) and lean littermates (controls, n = 7) were sacrificed at the age of 19 weeks." (PMID 22621761, 2012). "A trend was observed with self-reported hypertension (OR = 1.4, p = 0.08) and dyslipidemia (OR = 1.4, p = 0.08) while being treated with insulin and diabetes duration did not influence medication adherence." (PMID 22403654, 2012). "Traditionally, in clinical practice, endogenous insulin secretion is not measured and treatment decisions are made on the basis of glycaemic control and clinical diagnosis of diabetes subtype." (PMID 22681724, 2012). "In 2009, 51.1% of the T2DM respondents received oral antidiabetic medications alone, 12.5% received insulin plus oral antidiabetic agents, 9.6% received insulin alone, and 26.8% received no diabetes medications." (PMID 22917219, 2012). "The United Kingdom Prospective Diabetes Study (UKPDS) has clearly demonstrated that the progressive nature of T2DM reflects an ongoing decline in β-cell function without a change in insulin sensitivity." (PMID 22110477, 2012). "Diabetes mellitus is a group of metabolic diseases in which a person has high blood glucose either because the body does not produce enough insulin, or because cells do not respond to the insulin that is produced by the pancreas." (PMID 22611498, 2012). "TLR4 activation and expression increase in diabetes in response to hyperglycemia, and this was not prevented by insulin treatment." (PMID 22924123, 2012).
diabetes (continued). "While mice globally lacking IRS-2 develop diabetes due to insulin resistance and pancreatic β cell dysfunction, NesCreIrs2KO mice do not suffer from overt and progressive diabetes due to preservation of pancreatic β-cell mass and insulin concentration." (PMID 22383997, 2012). "Transdermal insulin delivery allows insulin to be absorbed through the skin and can be given anywhere on the body, regardless of the body composition of the person with diabetes." (PMID 23098076, 2012). "A nurse-driven insulin infusion protocol was developed and implemented in postoperative cardiothoracic surgical intensive care patients with or without diabetes." (PMID 24764523, 2012). "Moreover, it have been shown that intraepithelial CD8+γδ T cells prevent diabetes, and intraepithelial γδ T cells are required for induction of regulatory CD4+CD25+ T cells by oral insulin, in the neonatal thymectomy NOD mouse model of T1D." (PMID 22428018, 2012). "Mothers with type 2 diabetes mellitus have been included in order to compare insulin concentrations and as they should have no exogenous insulin present in their milk or blood." (PMID 22500167, 2012). "Even after oral hypoglycaemic agent or insulin users were excluded from the patients with diabetes, the same analysis found no change in the significance of the results (data not shown)." (PMID 22247968, 2012). "In head-to-head phase 3 clinical trials, exenatide b.i.d. and insulin (glargine and biphasic insulin aspart) provided similar glycemic control in patients whose diabetes was not controlled with oral antidiabetic medications (OADs)." (PMID 22714818, 2012). "In this study, we demonstrate that AG490 initiates remission of diabetes in newly diagnosed and established diabetic mice, no insulin was injected at any time, and sustained euglycemia was evident for several months following drug withdrawal." (PMID 22615750, 2012). "Routine monitoring of diabetics for insulin autoreactive T cells by diverse studies only reveals low affinity insulin-autoreactive T cells in diabetes subjects without treatment." (PMID 22905105, 2012). "Given the role played by pioglitazone and metformin in treatment of diabetes, results obtained from the study were expectable but the noticeable point was the effect of silymarin on decreasing blood sugar and insulin level, and HOMA index." (PMID 23087748, 2012). "Diabetes is a chronic metabolic disorder characterized by inappropriate hyperglycemia due to lack of or resistance to insulin, which contributes to ECD." (PMID 22611498, 2012). "At baseline (2004), 66.6% of the T2DM respondents received oral antidiabetic medications alone, 8.7% received insulin plus oral antidiabetic agents, 5.5% received insulin alone, and 19.2% received no diabetes medications." (PMID 22917219, 2012). "This investigation suggested that in addition to stimulation of insulin, genipin might protect the integrity of podocyte and delay the onset of DN through inhibition of UCP2 protein expression in diabetes." (PMID 22848482, 2012). "Not using insulin means denying the use of a gift that has been bestowed by Allah for the treatment of diabetes." (PMID 23497693, 2012). "Traditional diabetes therapies for insulin-dependent patients try to achieve normal glycemia by administrating synthetic insulin to control patient’s blood sugar level." (PMID 23612026, 2012). "Diabetes mellitus (DM) is a chronic metabolic disorder characterized by inappropriate hyperglycemia due to lack of or resistance to insulin." (PMID 22611498, 2012). "In this comprehensive model, the weighted genetic risk score associated with IGT (β = 0.15, p = 0.0003) after adjustment for gender, age, BMI, insulin sensitivity, LDL, HDL, triglycerides, use of lipid lowering drugs, use of antihypertensives and family history of diabetes." (PMID 22768041, 2012).
diabetes (continued). "The heterozygous mutant (S/A) mice did not spontaneously develop diabetes; however, on a 45% high fat diet, these mice showed glucose intolerance and insulin secretion defect in β cells." (PMID 21915177, 2012). "On the other hand, insulin-secreting cell lines like RIN, HIT, MIN, INS-1, βTC cells and also the glucagon-like peptide-1 (GLP-1) promoter, which is in gut L-cells and is a good candidate for diabetes mellitus gene therapy, are recently used." (PMID 23843817, 2012). "The healthcare professionals felt that some patients lacked knowledge and were reluctant to start insulin, especially those who had a short history of diabetes." (PMID 22469132, 2012). "In type-2 diabetes (T2D), which accounts for 90% of all diabetes, the β-cells largely remain intact but insulin is not released in sufficient amounts." (PMID 22177710, 2012). "The mean scores in insulin use knowledge were similar for those who attended and those who did not attend regular diabetes meetings." (PMID 23396799, 2012). "There are four main types of DM: type 1 -results from the autoimmune destruction of the pancreatic beta-cells; type 2: insulin metabolism or secretion disorder; secondary diabetes related to genetic predisposition, drug use, unknown cause; gestational diabetes." (PMID 22714855, 2012). "Since it is known that compliance to both OHA and insulin is poor in many diabetes patients, no conclusions about the efficacy of different medication types can be drawn." (PMID 22719972, 2012). "In both forms of diabetes, the metabolic consequences of the lack of insulin are exacerbated by oversecretion of glucagon." (PMID 22177710, 2012). "Optimal diabetes management is not achieved by many people with T1DM or insulin-treated T2DM who do not adjust their insulin regimens as needed." (PMID 23062116, 2012). "Although insulin resistance is a cardinal feature of type 2 diabetes, most people with insulin resistance do not develop diabetes because their pancreatic beta cells are able to compensate by increasing insulin production." (PMID 22253604, 2012). "In this cross-sectional study of asymptomatic middle-aged subjects without advanced diabetes, plasma insulin and obesity-related parameters were measured along with other cardiometabolic risk factors." (PMID 22748134, 2012). "Our study population consists of primary care patients with a mean age of 67 years and diabetes duration of 6 years who were not yet treated with insulin." (PMID 22679516, 2012). "This difference is probably due to our selection of well-controlled, no insulin using diabetes patients." (PMID 23039172, 2012). "Diabetes nurse educators are an important, but lacking resource for insulin initiation, with less than 600 diabetes nurse educators in the country serving a diabetes population of approximately 1.6 million." (PMID 22469132, 2012). "As insulin was initially not considered necessary for treatment of type 2 diabetes, it is known as non-insulin dependent diabetes mellitus (NIDDM) or Adult Onset Diabetes." (PMID 22611498, 2012). "As long as the pancreatic beta cells compensate for increasing insulin resistance with an augmented release of insulin, blood glucose will stay controlled, and the patient will not present, as per definition, with frank diabetes mellitus." (PMID 22577369, 2012). "Another barrier noticed by the health care professional is some patients with diabetes were facing negative influence and poor support from family members especially from their spouse to initiate insulin." (PMID 22469132, 2012). "Forty-one patients were classified as insulin sensitizers experienced (metformin) and 41 as controls (cirrhotic patients with type 2 diabetes mellitus without metformin treatment)." (PMID 23166628, 2012). "Previous pilot studies in animals or humans have employed topical insulin to accelerate wound healing in diabetes and, although these studies were not well designed, they all show an effect of insulin on this process." (PMID 22662132, 2012).